ENSG00000268465 (novel protein)
Gene: Protein-coding gene on chromosome 19 (48,465,837 to 48,472,431, forward strand). Ensembl gene ENSG00000268465.
Genetic constraint (gnomAD): Loss-of-function variants: 4 observed, 10.84 expected, observed/expected ratio (o/e) 0.37, 90% interval 0.18 to 0.84. Missense variants: 88 observed, 134.5 expected, observed/expected ratio (o/e) 0.65, 90% interval 0.55 to 0.78. Synonymous variants: 58 observed, 53.99 expected, observed/expected ratio (o/e) 1.07, 90% interval 0.87 to 1.34.